TBK1 (TANK binding kinase 1)
Description:
Serine/threonine kinase that plays an essential role in regulating inflammatory responses to foreign agents. Following activation of toll-like receptors by viral or bacterial components, associates with TRAF3 and TANK and phosphorylates interferon regulatory factors (IRFs) IRF3 and IRF7 as well as DDX3X. This activity allows subsequent homodimerization and nuclear translocation of the IRFs leading to transcriptional activation of pro-inflammatory and antiviral genes including IFNA and IFNB. In order to establish such an antiviral state, TBK1 form several different complexes whose composition depends on the type of cell and cellular stimuli. Plays a key role in IRF3 activation: acts by first phosphorylating innate adapter proteins MAVS, STING1 and TICAM1 on their pLxIS motif, leading to recruitment of IRF3, thereby licensing IRF3 for phosphorylation by TBK1. Phosphorylated IRF3 dissociates from the adapter proteins, dimerizes, and then enters the nucleus to induce expression of interferons. Thus, several scaffolding molecules including FADD, TRADD, MAVS, AZI2, TANK or TBKBP1/SINTBAD can be recruited to the TBK1-containing-complexes. Under particular conditions, functions as a NF-kappa-B effector by phosphorylating NF-kappa-B inhibitor alpha/NFKBIA, IKBKB or RELA to translocate NF-Kappa-B to the nucleus. Restricts bacterial proliferation by phosphorylating the autophagy receptor OPTN/Optineurin on 'Ser-177', thus enhancing LC3 binding affinity and antibacterial autophagy. Phosphorylates SMCR8 component of the C9orf72-SMCR8 complex, promoting autophagosome maturation. Phosphorylates ATG8 proteins MAP1LC3C and GABARAPL2, thereby preventing their delipidation and premature removal from nascent autophagosomes. Seems to play a role in energy balance regulation by sustaining a state of chronic, low-grade inflammation in obesity, which leads to a negative impact on insulin sensitivity (By similarity). Attenuates retroviral budding by phosphorylating the endosomal sorting complex required for transport-I (ESCRT-I) subunit VPS37C. Phosphorylates Borna disease virus (BDV) P protein. Plays an essential role in the TLR3- and IFN-dependent control of herpes virus HSV-1 and HSV-2 infections in the central nervous system. Acts both as a positive and negative regulator of the mTORC1 complex, depending on the context: activates mTORC1 in response to growth factors by catalyzing phosphorylation of MTOR, while it limits the mTORC1 complex by promoting phosphorylation of RPTOR. Acts as a positive regulator of the mTORC2 complex by mediating phosphorylation of MTOR, leading to increased phosphorylation and activation of AKT1 (By similarity). Phosphorylates and activates AKT1. Involved in the regulation of TNF-induced RIPK1-mediated cell death, probably acting via CYLD phosphorylation that in turn controls RIPK1 ubiquitination status. Also participates in the differentiation of T follicular regulatory cells together with the receptor ICOS.
Synonyms: NAK; AIARV; FTDALS4; IIAE8; T2K
Tractability: Small molecule: a structure with a bound ligand is known; a high-quality ligand is known; it belongs to a druggable protein family. PROTAC: it is named in the literature on targeted protein degradation; UniProt records ubiquitination sites on it; ubiquitination databases record sites on it; its protein half-life has been measured; a small molecule that binds it is known.
Target class: Enzyme; Other protein kinase group; Other protein kinase IKK family; Kinase; Protein Kinase
Chemical probes: BAY-985 (high quality), GSK8612 (high quality), TBK1 PROTAC 3i (high quality)
Safety:
Unwanted effects reported when the protein is acted on. In parentheses: how it was acted on, where the effect was seen, and who reports it.
cardiac arrhythmia (cardiovascular system; source: Lamore et al. (2017))
Gene: Protein-coding gene on chromosome 12 (64,452,090 to 64,502,114, forward strand). Ensembl gene ENSG00000183735.
Subcellular location: Cytoplasm
Subcellular location (Human Protein Atlas): Nucleoplasm; Vesicles
Pathways (Reactome):
Immune System: Activation of IRF3, IRF7 mediated by TBK1, IKKε (IKBKE); DDX58/IFIH1-mediated induction of interferon-alpha/beta; IRF3 mediated activation of type 1 IFN; IRF3-mediated induction of type I IFN; Interleukin-37 signaling; Negative regulators of DDX58/IFIH1 signaling; Regulation of TBK1, IKKε (IKBKE)-mediated activation of IRF3, IRF7; Regulation of TBK1, IKKε-mediated activation of IRF3, IRF7 upon TLR3 ligation; Regulation of innate immune responses to cytosolic DNA; STAT6-mediated induction of chemokines; TICAM1-dependent activation of IRF3/IRF7; TRAF3-dependent IRF activation pathway; TRAF6 mediated IRF7 activation
Disease: Potential therapeutics for SARS; SARS-CoV-1 activates/modulates innate immune responses; SARS-CoV-2 activates/modulates innate and adaptive immune responses
Signal Transduction: Regulation of TNFR1 signaling; TNFR1-induced proapoptotic signaling
Autophagy: PINK1-PRKN Mediated Mitophagy
Gene Ontology:
Molecular function: phosphoprotein binding; protein binding; protein serine kinase activity; protein serine/threonine kinase activity; RNA polymerase II-specific DNA-binding transcription factor binding; protein kinase activity; protein phosphatase binding; ATP binding; identical protein binding; nucleic acid binding
Biological process: activation of innate immune response; antiviral innate immune response; cytoplasmic pattern recognition receptor signaling pathway; innate immune response; negative regulation of TORC1 signaling; peptidyl-serine phosphorylation; peptidyl-threonine phosphorylation; positive regulation of autophagy; positive regulation of canonical NF-kappaB signal transduction; positive regulation of interferon-alpha production; positive regulation of interferon-beta production; positive regulation of macroautophagy; positive regulation of TORC1 signaling; positive regulation of transcription by RNA polymerase II; positive regulation of type I interferon production; protein phosphorylation; regulation of type I interferon production; T follicular helper cell differentiation; toll-like receptor 4 signaling pathway; canonical NF-kappaB signal transduction; cGAS/STING signaling pathway; defense response to virus; inflammatory response; macroautophagy; positive regulation of TORC2 signaling; and 8 more
Cellular component: cytoplasm; cytosol; nucleoplasm; serine/threonine protein kinase complex
Genetic constraint (gnomAD): Loss-of-function variants: 19 observed, 55.2 expected, observed/expected ratio (o/e) 0.34, 90% interval 0.24 to 0.5. The upper end of that interval is the gene's LOEUF score, 0.5, which puts it in group 2 of 6, group 1 being the genes least tolerant of losing a copy. Missense variants: 447 observed, 622.42 expected, observed/expected ratio (o/e) 0.72, 90% interval 0.66 to 0.78. Synonymous variants: 180 observed, 203.1 expected, observed/expected ratio (o/e) 0.89, 90% interval 0.78 to 1.
Gene-disease validity (ClinGen):
ClinGen rates the evidence that TBK1 causes each of these diseases.
frontotemporal dementia and/or amyotrophic lateral sclerosis 4 (autosomal dominant): Definitive. An amyotrophic lateral sclerosis that has material basis in mutation in the TBK1 gene on chromosome 12q14.
Homologues: Orthologues: chimpanzee TBK1 (99% identical), macaque TBK1 (99% identical), dog TBK1 (97% identical), guinea pig TBK1 (97% identical), rat Tbk1 (95% identical), pig TBK1 (94% identical), mouse Tbk1 (94% identical), rabbit TBK1 (94% identical), zebrafish tbk1 (71% identical), tropical clawed frog tbk1 (64% identical), Drosophila melanogaster IKKepsilon (36% identical). Paralogues in human: IKBKE (48% identical), IKBKB (21% identical), CHUK (20% identical).
Diseases named in the same sentence as TBK1 in open-access papers:
TBK1 is named in the same sentence as 298 diseases in open-access papers, as found by Europe PMC text mining. Sharing a sentence is not in itself a finding about the gene and the disease. The quoted sentences say what the papers report.
viral infection (278 papers, 2009 to 2026). "In any case, a diagnosis of AD or AR TBK1 deficiency should be considered in patients with severe viral infections with involvement of one or more organs." (PMID 41608123, 2025). "In contrast, humans harboring point mutations in TBK1 that result in a loss of its kinase activity are highly susceptible to severe viral infection." (PMID 36936901, 2023). "For example, during viral infection, TBK1 can interact with virus-associated pattern recognition receptors (such as RIG-I and TLR3) and become activated." (PMID 37515271, 2023). "Together, we concluded that ZNF268a mediates the recruitment of SETD4 to TBK1 and associated complexes upon viral infection." (PMID 37926288, 2023). "The reduced level of IRF-activating kinases is associated with a weaker type I IFN response downstream of RLR and cGAS activation, which likely explains the enhanced susceptibility of patients with TBK1 mutation to severe viral infection." (PMID 36936901, 2023). "To understand if the observed increase in viral infection during TBK1-deficiency is a consequence of type I interferon response inhibition, we examined viral infection in interferon-alpha/beta receptor (IFNAR)-silenced cells." (PMID 36044516, 2022). "PARP7 deficiency increases IFN-I signaling in response to viral infection by preventing TBK1-dependent suppression of the IFN-I activation cascade." (PMID 35055106, 2022). "Even RNA viruses, with much smaller genomes, encode multiple cGAS/STING/TBK1 pathway inhibitors, testifying to the importance of this pathway during viral infection." (PMID 34903048, 2021). "In our earlier study we had seen that viral infection causes phosphorylation of TBK1, IRF3, and NF-κB (p65)." (PMID 34214498, 2021). "To better describe molecular events underlying mTOR activation downstream of TBK1, we sought to determine how TBK1 engages with mTOR during viral infection." (PMID 33411856, 2021). "It has been reported that viral infection induces K48-linked and K63-linked ubiquitination of TBK1, which is essential to the activation of IFN-I signaling." (PMID 34908452, 2021). "Among the USP members, USP1 functions as a viral infection-induced physiological enhancer of TBK1 expression when bound to USP1 the K48-linked polyubiquitination of TBK1, resulting in enhanced TLR3/4 and RIG-I-induced IRF3 activation and IFNβ secretion." (PMID 34707613, 2021). "While TBK1 knockout is embryonically lethal due to liver apoptosis, IKKε knockout is viable but exhibits enhanced susceptibility to viral infection and elevated obesity in response to a high-fat diet." (PMID 30223576, 2018). "The association between ERRα and TBK1 prompted us to analyze the effect of TBK1 on ERRα expression in response to viral infection." (PMID 28591144, 2017). "Immunoprecipitation experiments demonstrated that NS3 binds to OPTN and, in cells expressing NS3, the association between OPTN and TBK1 was impaired after viral infection, accounting for the lower levels of TBK1 activation observed." (PMID 27538435, 2016). "During viral infection, GSK3β is known to associate with TBK1 and promote self-association and autophosphorylation at S172; however, the effect of GSK3β on TBK1 is independent of its kinase activity." (PMID 26656453, 2015). "TBK1 and IKKi both undergo Lys63-linked polyubiquitination following virus infection, presumably to recruit a signaling complex containing ubiquitin binding proteins that activate IRF3." (PMID 23308279, 2013). "Collectively, these data suggest that RNF11 is recruited to TBK1 and IKKi upon virus infection and attenuates their Lys63-linked polyubiquitination to block IFN-β production." (PMID 23308279, 2013). "TBK1 and IKKi are conjugated with Lys63-linked polyubiquitin chains during virus infection as a mechanism to promote IRF3 activation." (PMID 23308279, 2013). "Most TBK1 activity was restored 12 hr after viral infection in mib1−/− and MIB1/MIB2 double deficient MEFs." (PMID 23028469, 2012).
viral infection (continued). "Here we provide evidence that viral infection induces endogenous association of TBK1 with NEMO and this interaction depends upon association of NEMO ubiquitin binding domains with K63-ubiquitinated TBK1." (PMID 23028469, 2012). "TBK1/IKKε play a central role during the induction of IFNβ in response to virus infection, underscored by mouse knockout experiments that demonstrate the loss of virus-triggered IFNβ production in TBK1 −/− mice." (PMID 20174559, 2010). "AD or AR TBK1 deficiency should be considered in patients with severe viral infections." (PMID 41608123, 2025). "The very severe impairment of the I-IFN–related function of TBK1 observed in our experimental studies may explain the susceptibility of this patient to recurrent severe viral infections." (PMID 41608123, 2025). "We next aimed at investigating whether the discovered TBK1-mediated control of IKKε protein expression is involved in the differential susceptibility to viral infection between patients with TBK1 deficiency and TBK1 mutation." (PMID 36936901, 2023). "Upon viral infection, TBK1 gets activated, resulting in its K63- and K33-linked ubiquitination." (PMID 33525590, 2021). "Importantly, after viral infections, K63-linked poly-ubiquitination of TBK1 lysine residues as additional post translational modifications are required for type I IFN production." (PMID 29755463, 2018). "TBK1 was initially identified in the context of its ability to regulate NF-κB in vitro, yet later studies in TBK1 deficient mice demonstrated that TBK1 is an essential component of the IRF3 signaling pathway after both viral infection and stimulation of TLR3 by dsRNA31." (PMID 29343779, 2018). "As TBK1 has been implicated in IRF3 activation in response to viral infections, we then test whether TBK1 is involved in IRF3 activation, thus leading to type I IFN production following infection with IAV." (PMID 29312300, 2017). "TBK1 is ubiquitinated following viral infection even in the NEMO deficient cells." (PMID 23028469, 2012). "TBK-1 deficient embryonic fibroblasts have impaired IFN-α/β responses to virus infection." (PMID 21994610, 2010). "Indeed, the loss of TBK1 has a profound impact on type I IFN induction after viral infection." (PMID 27538435, 2016). "During viral infection, activated TBK1 undergoes nuclear translocation, where it is hijacked by UHRF2 to achieve gene-specific targeting at IFN-I loci." (PMID 42212328, 2026). "In macrophages, the deletion of USP19 following viral infection leads to an increase in TBK1 and activation of type I interferon signaling." (PMID 40083918, 2025). "IRF3 is the downstream effector of TBK1 and plays a crucial role in the immune defense against viral infection." (PMID 40036222, 2025). "ZNF268 is a zinc finger protein of the Kruppel-related family, which interacts with TBK1 to facilitate IRF3 activation during viral infection." (PMID 41153438, 2025). "A study reported that TRIM23 promotes the dimerization of TBK1 during viral infection, which in turn facilitates the phosphorylation of serine at site 403 of p62 to initiate autophagy." (PMID 40234418, 2025). "The related pathways of virus infection disease, such as herpes simplex virus 1 infection, human papillomavirus infection, and Epstein–Barr virus infection, were enriched, with TBK1 identified as a pivotal gene." (PMID 40423420, 2025). "AMPK is a potential candidate, as it has been shown to phosphorylate TBK1 at Ser511 in response to viral infection, facilitating downstream IRF3 recruitment and innate immune activation." (PMID 41282122, 2025). "Taken together, these results indicate that TXNIP negatively regulates MAVS aggregation during viral infection, thereby attenuating activation of downstream signaling pathways such as TBK1 and IRF3." (PMID 40628121, 2025). "A study reported that TRIM23 promotes TBK1 dimerization during viral infection and mediates autophagy through the TBK1-p62 axis." (PMID 40234418, 2025).
viral infection (continued). "IFI16 has an important role in antiviral defense by activating the canonical STING/TANK binding kinase 1 (TBK1)/IRF3 signaling pathway in response to viral infections." (PMID 40948780, 2025). "Our findings suggest that the activation of TBK1, mediated by Frk-dependent tyrosine kinase activity, is crucial for enhancing host antiviral defense during viral infections." (PMID 40012791, 2025). "Upon viral infection, activated TBK1 phosphorylates STING at a pLxIS motif, which is also present in MAVS." (PMID 40483467, 2025). "Early studies reported that TRAF3 activates TBK1 upon virus infection and that TBK1 and IRF3 then form a complex." (PMID 40234418, 2025). "In resting cells, IRF3 resides in the cytoplasm, but becomes phosphorylated by TBK1 and IKKε upon viral infection." (PMID 40700455, 2025). "AhR activation suppresses the constant defensive function against viral infection by suppressing TBK1." (PMID 40807684, 2025). "This process involves the stimulation of TBK1 phosphorylation at Tyr179 following viral infection in RAW264.7 macrophage cells." (PMID 39202404, 2024). "Given that mylipb is a decoy substrate for tbk1 and that tbk1 plays a critical role in the defence against viral infection, the function of mylipb in regulating the tbk1-mediated cellular antiviral immune response was investigated." (PMID 38739631, 2024). "These PTMs enhance TBK1 oligomerization after viral infection, thereby promoting TBK1 phosphorylation." (PMID 39201350, 2024). "We next assessed the effect of ADAP deficiency on the activation of IRF3 and TBK1, the key downstream signaling molecules of RIG-I in macrophages upon LPS stimulation or viral infection." (PMID 38776321, 2024). "During viral infection, activation of the TBK1/STING/IRF3 signaling cascade leads to the expression of IFN-I." (PMID 39345209, 2024). "Zebrafish tbk1 kinase activity and tbk1-mediated irf3 phosphorylation play an important role in defence against viral infection." (PMID 38739631, 2024). "As a pivotal member of the RLR pathway, TRAF3 is essential for activating the MAVS/TBK-1/IRF3 signaling pathway in response to viral infection." (PMID 39058724, 2024). "In the context of our study, we found that cardiotropic virus infection triggers ROS, which further oxidizes TBK1 and inhibits TBK1-mediated type I IFN production to enhance viral replication in both human and mouse cardiomyocytes." (PMID 38664417, 2024). "Activation of type I interferon is regulated by the IRF3 transcription factor, which undergoes phosphorylation-dependent activation by the upstream kinase, TBK1, during viral infection." (PMID 38495890, 2024). "IKBKE-deficient mice are viable, although they are hypersusceptible to some viral infections, whereas TBK1-knockout mice die at embryonic day 15 from TNF-induced apoptosis in the liver." (PMID 37937644, 2023). "cGAS/STING pathway plays a central role in immune defense against tumors and viral infections, where TANK-binding kinase 1 (TBK1) recruitment to STING further activates both NF-κB and interferon regulatory factor 3 (IRF3)." (PMID 38283361, 2023). "Despite the known correlation between OPTN and TBK1, we surprisingly found that viral infection in TBK1 KO cells was comparable to that in the wildtype counterparts (WT)." (PMID 38019030, 2023). "During viral infection, many negative regulators were reported to degrade TBK1, including E3 ligase, host factors, and viral factors." (PMID 37352355, 2023). "PGAM5 regulates the activity of inflammasome and caspase 1 in BMDMs and contributes to IFN-β production in response to viral infection by promoting the TBK1 (TANK-binding kinase 1)/IFN regulatory factor 3 (IRF3) signaling pathway." (PMID 37771598, 2023). "DNA sensors, including IFI16, DDX41, and cyclic GMP-AMP (cGAMP) synthase (cGAS), play a major role in response to virus infections through activating the canonical STING/TBK-1/IRF3 signaling pathway." (PMID 37410794, 2023).